RPL37 (ribosomal protein L37)
Description:
Component of the large ribosomal subunit. The ribosome is a large ribonucleoprotein complex responsible for the synthesis of proteins in the cell.
Synonyms: L37; eL37
Tractability: Small molecule: an approved drug acts on it; a structure with a bound ligand is known; a high-quality ligand is known. PROTAC: ubiquitination databases record sites on it; its protein half-life has been measured; a small molecule that binds it is known. Other modalities: a drug acting on it is in phase 2 or 3 trials.
Gene: Protein-coding gene on chromosome 5 (40,825,262 to 40,835,269, reverse strand). Ensembl gene ENSG00000145592.
Subcellular location: Cytoplasm
Pathways (Reactome):
Metabolism of proteins: Eukaryotic Translation Termination; Formation of a pool of free 40S subunits; GTP hydrolysis and joining of the 60S ribosomal subunit; L13a-mediated translational silencing of Ceruloplasmin expression; PELO:HBS1L and ABCE1 dissociate a ribosome on a non-stop mRNA; Peptide chain elongation; Ribosome Quality Control (RQC) complex extracts and degrades nascent peptide; SRP-dependent cotranslational protein targeting to membrane; ZNF598 and the Ribosome-associated Quality Trigger (RQT) complex dissociate a ribosome stalled on a no-go mRNA
Metabolism of RNA: Major pathway of rRNA processing in the nucleolus and cytosol; Nonsense Mediated Decay (NMD) enhanced by the Exon Junction Complex (EJC); Nonsense Mediated Decay (NMD) independent of the Exon Junction Complex (EJC)
Cellular responses to stimuli: Response of EIF2AK4 (GCN2) to amino acid deficiency
Developmental Biology: Regulation of expression of SLITs and ROBOs
Disease: Viral mRNA Translation
Metabolism: Selenocysteine synthesis
Gene Ontology:
Molecular function: MDM2/MDM4 family protein binding; structural constituent of ribosome; ubiquitin ligase inhibitor activity; RNA binding
Biological process: cleavage in ITS2 between 5.8S rRNA and LSU-rRNA of tricistronic rRNA transcript (SSU-rRNA, 5.8S rRNA, LSU-rRNA); cytoplasmic translation; negative regulation of myoblast fusion; spermatogenesis; striated muscle contraction; translation
Cellular component: cytoplasm; cytosolic large ribosomal subunit; cytosolic ribosome; cytosol; ribosome; synapse
Genetic constraint (gnomAD): Loss-of-function variants: 1 observed, 12.21 expected, observed/expected ratio (o/e) 0.0819, 90% interval 0.028 to 0.39. The upper end of that interval is the gene's LOEUF score, 0.39, which puts it in group 1 of 6, group 1 being the genes least tolerant of losing a copy. Missense variants: 96 observed, 129.06 expected, observed/expected ratio (o/e) 0.74, 90% interval 0.63 to 0.88. Synonymous variants: 52 observed, 45.61 expected, observed/expected ratio (o/e) 1.14, 90% interval 0.91 to 1.44.
Homologues: Orthologues: chimpanzee RPL37 (100% identical), guinea pig RPL37 (100% identical), mouse Rpl37 (100% identical), pig RPL37 (100% identical), rat Rpl37l1 (100% identical), zebrafish rpl37 (93% identical), macaque RPL37 (81% identical), tropical clawed frog rpl37 (78% identical).
Diseases named in the same sentence as RPL37 in open-access papers:
RPL37 is named in the same sentence as 15 diseases in open-access papers, as found by Europe PMC text mining. Sharing a sentence is not in itself a finding about the gene and the disease. The quoted sentences say what the papers report.
breast carcinoma (3 papers, 2019 to 2022). "RPLP2 and RPL37, both encoding for ribosomal proteins, were identified as tumor suppressor genes due to their silencing in breast cancer tissues." (PMID 35622738, 2022). "For the first time in this study, we used a comprehensive in silico approach and identified five proto-oncogenes (TUBA1B, SLC2A1, PGK1, CCND1, and NCAPD2) and two tumor suppressor genes (RPLP2, RPL37) as novel therapeutic targets against breast cancer." (PMID 35622738, 2022). "But the TCGA analysis confirmed hypermethylation silencing of only the RPLP2 and RPL37 genes in human breast cancer tissues." (PMID 35622738, 2022). "In this study, for the first time, we report five oncogenes (TUBA1B, SLC2A1, PGK1, CCND1, and NCAPD2) and two tumor suppressors’ genes (RPLP2, RPL37) as novel therapeutic targets in breast cancer." (PMID 35622738, 2022). "Similarly, in an experimental study on breast cancer patients subjected to neoadjuvant chemotherapy RPL37 expression along with a few other genes was shown to distinguish responsive from non-responsive tumors suggesting protective roles of both genes." (PMID 35622738, 2022). "In breast cancer tissues, RPLP2 and RPL37 were found to be downregulated and their promoter region was hypermethylated." (PMID 35622738, 2022). "Furthermore, the other two hub genes, RPL37 and RPL23, were identified in the expression profiling of the cDNA-based microarray in response to 5-FU in a breast cancer cell though without subsequent validation." (PMID 31662984, 2019).
colon cancer (2 papers, 2007 to 2018). "We found that calcitriol treatment in both right-sided and left-sided colon cancer causes a downregulation of ribosomal protein L37 and protein S100A10." (PMID 29324674, 2018). "It is interesting to note that RPL37 overexpression in prostate cancer, colon cancer cell lines and clinical specimens have been reported." (PMID 17543121, 2007).
Alzheimer disease (1 paper, 2024). A progressive, neurodegenerative disease characterized by loss of function and death of nerve cells in several areas of the brain leading to loss of cognitive function such as memory and language. "The down-regulated DEGs in DM versus NN were primarily focused on ribosome (approximately 80 DEGs, including RPL37 and RPS11), Alzheimer’s disease (about 86 DEGs), and cardiac muscle contraction (about 22 DEGs, such as UQCRQ and TNNC1)." (PMID 38660519, 2024).
cognitive decline (1 paper, 2021). "DUSP22 and RPL37 associated with rate of cognitive decline as measured by the slope of mPACC, and AMPD3 associated with the slope of CDR-SB and MCI to AD conversion status are also abundantly expressed in microglia." (PMID 34654479, 2021).
glioma (1 paper, 2023). A benign or malignant brain and spinal cord tumor that arises from glial cells (astrocytes, oligodendrocytes, ependymal cells). "Comparing ACTA2 expression in initial and recurrent samples from the same glioma patients, we noted that ACTA2/RPL37 increased nearly twofold in recurrent cases (median value: 2.05, range: 0.12–17.39) compared to initial cases (median value: 0.90, range: 0.04–4.10)." (PMID 37891844, 2023).
lung carcinoma (1 paper, 2013). "RPL37, RPS15, and RPS20 were cloned into a mammalian expression vector and transfected into H1299 lung carcinoma cells alongside Mdm2." (PMID 23874713, 2013).
ovarian carcinoma (1 paper, 2024). A malignant neoplasm originating from the surface ovarian epithelium.
cancer (8 papers, 2007 to 2025). A tumor composed of atypical neoplastic, often pleomorphic cells that invade other tissues. "It has been suggested that the many phosphorylation sites found on RPL37 may be the substrate for a regulatory cascade of kinases that can be exploited by cancer for autonomous growth signaling and protein synthesis." (PMID 29324674, 2018). "Furthermore, UBA52 and RPL37 are related to ribosome pathway, and PRKC is related to the “cancer” pathway, as indicated by the KEGG analysis." (PMID 27329587, 2016). "The real-time PCR results for AQP3 and RPL37 did not concur with L-SAGE data and may be due to interindividual differences rather than a representation of changes present in CIN lesions or cancer." (PMID 17543121, 2007).
tumor (8 papers, 2020 to 2025). "A tumour suppressive role for RPL37 is also supported by a retrospective study of 333 patients with non-metastatic locally advanced breast carcinoma." (PMID 40940922, 2025). "Its parent gene, RPL37, plays a crucial role as a ribosomal protein in protein translation and participates in regulating the tumor suppression." (PMID 41019085, 2025). "Through docking analysis, the study showed an association of RPL37 with the C-terminal tail of β-catenin, E-cadherin and APC, through which RPL37 inhibits tumour cell migration." (PMID 40940922, 2025).
infection (4 papers, 2021 to 2025). The state of being infected such as from the introduction of a foreign agent such as serum, vaccine, antigenic substance or organism. "In contrast, the biological processes downregulated with infection include ribosomal biogenesis (Rpl3, Rpl37, Rps5, Rpl11, Rplp1, Rpl28, Rpl19, Rps28, Rps14)." (PMID 35789215, 2022). "Among the ribosomal proteins, Treacle ribosome biogenesis factor 1(TCOF1), nuclear transport factor 2 like export factor 2(NXT2), ribosomal protein L37(RPL37), ribosomal protein L29 (RPL29) and mitochondrial ribosomal protein S18A(MRPS18A) are all up-regulated in the early stages of infection." (PMID 34092256, 2021).
infectious disease (1 paper, 2022). A disorder directly resulting from the presence and activity of a microbial, viral, or parasitic agent in humans. "In the case of the pre-diagnostic markers for CD4+ T cells, the upregulated genes included ribosomal proteins (e.g. RPL39, RPL37, RPS28 and RPS21) that showed enrichments in pathways related to translation and “Infectious disease”." (PMID 35371081, 2022).
RPL37 also shares sentences with these, for which no sentence is quoted: lymphoma (1 paper); multiple myeloma (1); osteosarcoma (1); prostate carcinoma (1).